CXCR2 (C-X-C motif chemokine receptor 2)
Diseases named in the same sentence as CXCR2 in open-access papers (continued):
Sharing a sentence is not in itself a finding about the gene and the disease.
prostate carcinoma (continued). "Thus, targeting CXCR2 could not only reverse CD47/SIRPα-mediated resistance to phagocytosis and suppress M2 macrophage polarization but also counteract NED in prostate cancer cells." (PMID 41163221, 2025). "Furthermore, treatment with the CXCR2 inhibitor SB225002 blocked HO-1 expression and upregulated endogenous ROS and H2O2-induced ROS levels in prostate cancer cells, indicating that CXCL5 affects endogenous ROS and H2O2-induced ROS, and is dependent on HO-1 and CXCR2." (PMID 39765818, 2024). "CXCR2 antagonists are currently in clinical trials to block MDSC recruitment to tumors and the pre-metastatic niche (NCT03177187 in metastatic castration-resistant prostate cancer (not yet recruiting)." (PMID 30873179, 2019).
lung carcinoma (64 papers, 2004 to 2025). "In the mutant Kras-driven lung cancer mouse model, CXCR2-mediated and neutrophil-induced inflammation was associated with the malignant transformation of normal epithelial cells to lung adenocarcinoma." (PMID 39061147, 2024). "In lung cancer patients, a significant association between elevated CXCR2 expression levels and prognosis has been reported." (PMID 39061147, 2024). "Previous studies on lewis lung carcinoma mouse models showed that blockade of chemokine receptor CXCR2 or CXCR2-deficient mice reduced angiogenesis and tumor growth." (PMID 37158964, 2023). "Although most studies link CXCR2 to carcinogenesis, one study found that a single-nucleotide polymorphism (SNP) in CXCR2's 3' untranslated region (UTR) induces greater CXCL receptor expression but is associated with a lower risk of lung cancer." (PMID 36164329, 2022). "In lung cancer model of this study, CXCR2-associated chemokines were significantly up-regulated and the expression of CXCR2 on surface of neutrophils was increased following tumor stimulation." (PMID 33814009, 2021). "The expression of CXCR2 was elevated in both human lung cancer stroma and tumor cells, which was associated with patients’ prognosis." (PMID 33814009, 2021). "In the present study, CXCR2 was overexpressed in lung cancer tissues and associated with poor overall survival of patients with NSCLC." (PMID 33814009, 2021). "Lung cancer cells continuously secrete CXCR2-associated chemokines, and high level expressions of those chemokines promote tumor progression and metastasis." (PMID 33814009, 2021). "In this research, we found CXCR2 expression level was significantly associated with prognosis and survival of patients with lung cancer." (PMID 33814009, 2021). "Previous studies have already proved that high level of CXCR2 on lung cancer cells is associated with smoking and poor prognosis in clinical patients." (PMID 33814009, 2021). "We employed mouse Lewis lung carcinoma cell line and human lung cancer cell line H460, which expressed CXCR2 on the surface and secreted CXCR2-associated chemokines, such as CXCL1, CXCL2, CXCL5 and MIF." (PMID 33814009, 2021). "The high affinity of CXCR2 to chemokines has been shown to be associated with the prognosis of patients with many cancers, including glioblastoma, colon cancer, lung cancer, hepatocellular carcinoma, and pancreatic cancer." (PMID 34238119, 2021). "A common genetic variation rs1126579 (C > T) located in the 3′UTR of the CXCR2 (IL8RB) was found to be associated with a reduced risk of lung cancer with strong evidence." (PMID 28827732, 2017). "This provides a baseline for future clinical trials and/or prevention trials using the IL-8/CXCR2 pathway or NE inhibitors in patients with lung cancer and high risk COPD patients." (PMID 24321240, 2013). "Notably, a number of GPCRs, including CXCR4, CXCR2 and EP receptors, have been implicated in the organ-specific metastasis of lung cancer." (PMID 26760963, 2016). "In a mouse model of lung cancer overexpressing CXCR2, an increase in the infiltration of TANs was shown, while an inhibition of CXCR2 ameliorated this infiltration as well as increased antitumor T-cell activity, through the promotion of CD+ T cell activation." (PMID 39982274, 2025). "In a murine lung cancer model, CXCR2+ neutrophils TGF-β and Arg-1 were significantly increased, causing immunosuppression and allowing tumor cells to escape immune attack." (PMID 39114657, 2024). "In lung cancer cell-challenged mice, increased CXCLs/CXCR2 signaling, Arg-1, and TGF-β levels were observed, accompanied by the significant infiltration of TANs in tumor tissues." (PMID 39061147, 2024). "The CXCLs/CXCR2 axis plays a vital role in apoptosis, epithelial-to-mesenchymal transition, and cell proliferation in lung cancer, and unresolving neutrophilic airway inflammation of patients with COPD and severe asthma." (PMID 36968579, 2023).
lung carcinoma (continued). "Regarding lung cancer, it has been reported that β-arrestin 2 can modulate tumorigenesis by regulating inflammation and angiogenesis through activation of CXCR2 and NF-κB in a murine model of lung cancer." (PMID 37443143, 2023). "The targeting of CXCR2 inhibited lung cancer progression and promoted the cytotoxic effects of cisplatin." (PMID 37509311, 2023). "SB225002, a specific CXCR2 inhibitor, promoted apoptosis and senescence in lung cancer cells while decreasing EMT and proliferation." (PMID 36164329, 2022). "In a mouse model of lung cancer, the depletion of β-arrestin 2 activated CXCR2 and NF-κB, leading to tumor growth and angiogenesis." (PMID 36010884, 2022). "Zhou et.al indicated that Schwann cells activated the PI3K/AKT/GSK-3β pathway and augmented the expression of Snail and Twist in lung cancer cells through CXCL5/CXCR2 axis, thus promoting the EMT and metastasis of lung cancer." (PMID 36522730, 2022). "It was shown that the CXCL/CXCR2 axis was activated in resistant cells after cisplatin treatment, allowing CXCR2 to be highly expressed in human lung cancer tissues." (PMID 36313710, 2022). "The result of flow cytometric analyses of the tumor microenvironment of mouse lung cancer mode showed that the percentage of CXCR2-positive neutrophils were significantly increased, whereas the percentage of monocytes remained unchanged." (PMID 33814009, 2021). "In this study, we used tumor tissue microarray of lung cancer patients and established animal models to investigate the role CXCLs/CXCR2 signaling played in lung cancer." (PMID 33814009, 2021). "Nevertheless, it is unclear what role CXCR2 and its chemokines are playing in the therapy of lung cancer." (PMID 33814009, 2021). "Pharmacological inhibition of CXCR2 significantly decreased lung cancer progression with ameliorated recruitment of neutrophils into tumor microenvironment." (PMID 33814009, 2021). "By IHC analysis, the increased expression of CXCR2 and neutrophil infiltration were both confirmed in lung cancer." (PMID 33814009, 2021). "The expression of CXCR2 is higher in tumor stroma than tumor cells in human lung cancer and correlates with poor prognosis." (PMID 35011369, 2021). "CXCLs/CXCR2 autocrine loop exist in lung cancer cells and participate in the regulation of apoptosis, proliferation, senescence, and EMT of tumor cells through p38/ERK MAPK pathway." (PMID 33814009, 2021). "Our finds verify the therapeutic effects of targeting CXCR2 in lung cancer and uncover the potential mechanism for the increased sensitivity to chemotherapeutic agents by antagonists of CXCR2." (PMID 33814009, 2021). "In mice of lung cancer model, blockade of CXCR2 inhibits lung tumor growth via decreasing immune suppressive neutrophils infiltration, augmenting the activation of CD8+ T cells and improved therapeutic effect of cisplatin by modulating tumor microenvironment." (PMID 33814009, 2021). "The data indicated that high expression of CXCR2 in human lung cancer tissues, both in stroma and parenchyma, was significantly associated with shorter survival." (PMID 33814009, 2021). "In vivo, IL-17 increased net angiogenic activity and the growth of human nonsmall cell lung cancer by encouraging CXCR2-dependent angiogenesis, according to the same research community." (PMID 34336101, 2021). "We also compared mRNA levels of CXCR1 and CXCR2 in lung cancer and normal tissues from same patient (a group of 8)." (PMID 26087179, 2015). "We report increased mRNA levels of CXCR1 and CXCR2 in human lung cancer tissues compared to normal counterparts." (PMID 26087179, 2015). "Our results suggest that G31P blockage of CXCR1 and CXCR2 can inhibit human lung cancer cell growth and metastasis, which offers potential therapeutic opportunities." (PMID 26087179, 2015). "This provides a baseline for future clinical trials using the IL-8/CXCR2 pathway or NE inhibitors in patients with lung cancer." (PMID 24321240, 2013).
lung carcinoma (continued). "We conclude that lung cancer promotion by inflammation is partly mediated by activation of the IL-8/CXCR2 pathway and subsequent recruitment of neutrophils and release of neutrophil elastase." (PMID 24321240, 2013). "Taken together, we confirmed that neutrophils play a very important role in the promotion of lung cancer which is strongly mediated through the IL-8/CXCR2 pathway and release of NE and development of a type 2 protumor microenvironment." (PMID 24321240, 2013). "The induction of CXCL8 was significant in HBEC4 and SKMES-1 (p<0.05), as was the increase in CXCR1 and CXCR2 in both the lung cancer cell lines (A549 - p<0.05, SKMES-1 – p<0.01) and CXCR1 in HBEC4 (p<0.05)." (PMID 21298036, 2011). "Inhibition of CXCR2 function on endothelial cells has been shown to inhibit tumor growth, for lung cancer and renal cell cancer models." (PMID 20652010, 2010). "Notably, pharmacological inhibition of CXCR2 signaling has been shown to effectively enhance the therapeutic efficacy of lung cancer immunotherapy." (PMID 41254689, 2025). "Senescent cancer cells promoted CXCR2 expression and mediated the resistance against therapy, meanwhile, inhibition of CXCR2 was found to promote cancer cell senescence process, then improved the survival period of patients with Head-and-Neck and lung carcinoma." (PMID 38184636, 2024). "Given that neutrophils express CXCR2, we hypothesized that lung cancer-secreted CXCL5 may attract neutrophils in peripheral blood mononuclear cells (PBMCs) to enter the TME." (PMID 39034411, 2024). "Meanwhile, based on our study, blockade of CXCR2 could improve the traditional therapy against lung cancer, such as cisplatin." (PMID 33814009, 2021). "Furthermore, patients with lung cancer were divided into CXCR2-high and CXCR2-low groups according to the Youden’s index of receiver operating characteristic (ROC) curves for prognosis of lung cancer." (PMID 33814009, 2021). "Several studies have explored the role of CXCLs/CXCR2 axis in lung cancer." (PMID 33814009, 2021). "All these data suggested that CXCR2 could promote lung cancer cells proliferation and anti-apoptosis." (PMID 33814009, 2021). "CXCLs/CXCR2 axis plays an important role in progression of cancer including lung cancer." (PMID 33814009, 2021). "Based on the features of the tumor microenvironment in lung cancer models, we reasoned that pharmacological CXCR2 inhibition might lead to anti-tumor response via regulation of neutrophils infiltration and repression of tumor cells." (PMID 33814009, 2021). "A study to determine the protumour effects of IL-17 or Th17 in human nonsmall cell lung cancer (NSCLC) when subcutaneously injected into SCID mice showed transfection of IL-17 increased NSCLC growth in vivo (SCID mice) via promoting CXCR2-dependent angiogenesis." (PMID 34336101, 2021). "In addition, previous studies have demonstrated that CXCR2 plays a critical role in cancers, such as lung cancer, laryngeal squamous cell carcinoma, astrocytic tumors, pancreatic ductal carcinoma, clear-cell renal cell carcinoma and hepatocellular carcinoma." (PMID 29599927, 2018). "Furthermore, it has also been shown in a murine model that depletion of CXCR2 inhibits tumor growth and angiogenesis of lung cancer." (PMID 26087179, 2015). "On the basis of above information, we hypothesized that inhibition of CXCR1 and CXCR2 by G31P might attenuate tumorigenesis of lung cancer." (PMID 26087179, 2015). "Histopathologic analysis of lung tissue from SBZ treated CC-LR mice showed that CXCR2 inhibition prevented lung cancer progression, with most of the lung tumors remaining at the early stage with less inflammatory cell infiltration both in the presence and absence of NTHi exposure." (PMID 24321240, 2013). "This is similar to the findings from other groups showing that CXCR2 inhibition using a neutralizing antibody inhibits the progression of premalignant alveolar lesions by reducing vascular density in another mouse model of lung cancer." (PMID 24321240, 2013).
lung carcinoma (continued). "However, it has also been demonstrated in a murine model that depletion of CXCR2 inhibits tumour growth and angiogenesis in lung cancer." (PMID 20429924, 2010). "Thus neutrophil antagonism with CXCR2 inhibitor could potentially serve as a therapeutic approach for improving the therapeutic efficacy of immune checkpoint inhibitor treatments in lung cancer." (PMID 41254689, 2025). "Thus, CXCR2 might play a role for M2-macrophages assisting lung carcinomas to facilitate neoangiogenesis." (PMID 29976164, 2018). "Compared with PBNs in lung carcinomas patients, increased levels of CCR5, CCR7, CXCR3, and CXCR4 are expressed in TANs, whereas CXCR1 and CXCR2 expression are downregulated." (PMID 41254689, 2025). "Furthermore, in tumor-associated neutrophils (TANs), CXCR2 mediates recruitment and protumor polarization, as N2 and SB225002 can have anti-tumor activity by inhibiting N2 TAN accumulation and enhance radiotherapy in nasopharyngeal carcinoma and synergizing with cisplatin in lung carcinomas." (PMID 41155662, 2025). "Blocking CXCR2 also resulted in the reduced infiltration of TANs, enhanced CD8+ T-cell activation, and the enhanced efficacy of traditional lung cancer chemotherapy like cisplatin." (PMID 39061147, 2024). "CXCR2 and CCR2 are the most extensively studied chemokine receptors in preclinical studies of lung cancer." (PMID 39114657, 2024). "Overall, CXCR2, CXCR4, CCR2 are currently the most extensively studied chemokine receptors in NSCLC and are considered potential biomarkers for lung cancer." (PMID 39114657, 2024). "The neutrophil hN3 subtype is defined by high expression of CXCR2, which has been shown to inhibit CD8 T-cell activation within the lung cancer microenvironment." (PMID 37024582, 2023). "The result of flow cytometric analysis demonstrated that CXCR2 was obviously expressed in murine cell line, LL2 (Lewis lung carcinoma, LLC) cell and human lung cancer cell line, A549, PC-9, and H460." (PMID 33814009, 2021). "A recent study has shown that inhibition of CXCR2 using SB225002, a CXCR2 inhibitor, significantly decreases infiltration of TANs in tumor tissues and suppresses tumor growth in a murine lung cancer model." (PMID 34885241, 2021). "Blockade of CXCR2 decreasse neutrophil infiltration in the TME and enhances antitumor T-cell activity and the antitherapeutic effects of cisplatin in lung cancer." (PMID 35011369, 2021). "Selective inhibitor of CXCR2, SB225002, was confirmed to inhibit the proliferation of lung cancer cells in a both time-dependent and dose-dependent manner." (PMID 33814009, 2021). "Inhibition of CXCR2 promoted apoptosis, senescence, epithelial-to-mesenchymal transition (EMT), and anti-proliferation of lung cancer cells." (PMID 33814009, 2021). "Inhibition of CXCR2 and its ligand CXCL8 significantly inhibits proliferation and migration of lung cancer cells and decreases angiogenesis." (PMID 33814009, 2021). "The lung cancer A549 cells, H157 cells, H460 cells and LLCs were shown to be CXCL5 receptor CXCR2 positive." (PMID 31819035, 2019). "CXCL1 functions through CXCR2, a G protein-coupled receptor that transactivates EGFR in ovarian and lung cancers." (PMID 26462152, 2015). "Our results showed that all the lung cancer cell lines tested expressed CXCR1 and CXCR2 except A549." (PMID 15545974, 2004). "In this study, we investigated the expression of IL-8 and its receptors, CXCR1 and CXCR2, in a panel of NSCLC and SCLC cell lines and characterised the mitogenic role of IL-8 in lung cancer growth." (PMID 15545974, 2004). "CXCR2 signaling essentially promotes senescence which is hypothesized to be a factor in the pathogenesis of COPD and lung cancer." (PMID 27826243, 2016). "Neutrophil depletion, CXCR2 inhibition, and lack of neutrophil elastase (NE) all resulted in significant tumor reduction in our K-ras mutant mouse model of lung cancer." (PMID 24321240, 2013).
lung carcinoma (continued). "Since the expression of CXCR1 and CXCR2 has not been studied in lung cancer cells, we next examined the expression of these receptors on cell surface by flow cytometry." (PMID 15545974, 2004). "The involvement of IL-8, CXCR-1 and CXCR-2 has been extensively investigated in different diseases such as pyelonephritis, hepatitis B, rapid disease progression of HIV-1+, lung diseases, such as chronic obstructive pulmonary disease and asthma, bronchiectasis, systemic sclerosis and lung cancer." (PMID 22051099, 2011). "CXCR1 and CXCR2 were found on a variety of tumour cells, but have not been reported in lung cancer." (PMID 15545974, 2004). "In our experiments, by using CXCR2 inhibitor SBB225002, CXCLs/CXCR2 axis was found to promoted lung cancer cells proliferation and EMT, and inhibited lung cancer cells apoptosis and senescence via p38/ERK, not JNK, MAPK pathway." (PMID 33814009, 2021). "Zhu found that cell proliferation was significantly reduced by anti-CXCR1 antibody but not by anti-CXCR2 antibody and concluded that the mitogenic function of CXCL8 in lung cancer is mediated mainly by CXCR1 receptor." (PMID 20429924, 2010).